HSF2 (heat shock transcription factor 2)
Diseases named in the same sentence as HSF2 in open-access papers (continued):
Sharing a sentence is not in itself a finding about the gene and the disease.
cancer (continued). "It is likely that HSP90 participates in the regulation of HSR in a more prevalent and complex manner than previously anticipated, to which HSF2 adds an additional exciting and novel aspect, with potential aspects of cancer treatment." (PMID 34331200, 2021). "HSF2 expression was associated with TMB in 9 cancer types and associated with MSI in 5 cancer types, while there was a correlation between HSF2 expression and DNA methylation in 27 types of cancer." (PMID 35087869, 2021). "Next, we investigated the interrelationship between HSF2 expression and the prognosis of pan-cancer patients, including overall survival (OS), disease-specific survival (DSS), disease-free interval (DFI), and progression-free interval (PFI)." (PMID 35087869, 2021). "GSEA was further performed to explore the signaling pathways and molecular mechanisms that were differentially affected by HSF2 in human cancers." (PMID 35087869, 2021). "Here, we observed that the expression of HSF2 was associated with TMB and MSI in several cancer types." (PMID 35087869, 2021). "Intriguingly, using closed form ATP-bound HSP90 mutants that can be co-precipitated with HSF1, a known facilitator of cancer, we show that also endogenous HSF2 co-precipitates with HSP90." (PMID 34331200, 2021). "A significant correlation between HSF2 expression and the prognosis of cancer patients was observed." (PMID 35087869, 2021). "Third, the effects of HSF2 on immune cell infiltration and immunotherapy in human cancer require experimental and clinical validation." (PMID 35087869, 2021). "Kaplan-Meier analysis and Cox regression were applied to explore the prognostic significance of HSF2 in different cancers." (PMID 35087869, 2021). "We also estimated HSF2 expression in paired cancer tissues and adjacent normal tissues in pan-cancer using TCGA datasets." (PMID 35087869, 2021). "We investigated HSF2 expression in various types of cancers and their corresponding normal tissues according to the TCGA database and observed that HSF2 was differentially expressed in 14 types of cancer." (PMID 35087869, 2021). "Cancer patients were separated into high-expression and low-expression groups based on HSF2 expression." (PMID 35087869, 2021). "Regarding the OS analysis, Cox regression results from 33 types of cancer suggested that HSF2 expression was markedly related to OS in 6 types of cancer, including ACC, GBM, KICH, KIRP, LIHC, and PAAD." (PMID 35087869, 2021). "After combining the data from TCGA and GTEx, the expression difference of HSF2 achieved significance in 25 out of 33 cancer types." (PMID 35087869, 2021). "The results indicated that high expression of HSF2 was a risk factor and associated with poor OS, DSS, DFI, and PFI in some cancers but seemed to be protective in KIRC and PAAD." (PMID 35087869, 2021). "In the present study, we comprehensively investigated the expression dysregulation and prognostic significance of HSF2, and the relationship with clinicopathological parameters and immune infiltration across cancers." (PMID 35087869, 2021). "Apart from HSF1, recent studies have identified HSF2 as an important regulator of gene networks that affects cancer progression and survival." (PMID 32408596, 2020). "Further studies, however, are required to determine if this HSF2 induction phenomenon occurs in other cancer cell lines and if it can be prevented." (PMID 30220976, 2018). "This pioneer study defines a new cancer research axe focused on HSF2 that definitely deserves further investigation." (PMID 24212658, 2011). "The roles of HSF1 and HSF2 in cancer have been explored more in depth in other reviews." (PMID 40457168, 2025).
cancer (continued). "Given the recent findings that the interaction between HSF1 and HSF2 is essential for cancer gene expression 24, 129, an important role of HSF2 in cancer development may become increasingly significant." (PMID 37153737, 2023). "List of studies on the relationship between HSF2 and cancers." (PMID 36430241, 2022). "As described, the relationship between HSF1 and cancer has been studied since the first discovery; however, whether HSF2 affects cancer cell survival and other tumor characteristics had been not clearly shown." (PMID 36430241, 2022). "HSF2 has been revealed to be deeply involved and/or to have indispensable roles in many cancers." (PMID 36430241, 2022). "In this section, we showed that many cancers are activated by HSF2." (PMID 36430241, 2022). "The relationship between cancer and HSF2 was discovered in this decade." (PMID 36430241, 2022). "HSF2 is involved in 10 or more kinds of cancers (carcinogenesis and/or progression)." (PMID 36430241, 2022). "In view of the pathological and clinical significance of HSF2 across different cancer types, we also investigated whether HSF2 could be used as a potential biomarker for the early diagnosis of human cancers." (PMID 35087869, 2021). "Hence, a comprehensive analysis of HSF2 expression and the prognostic value of HSF2 in different types of cancer is urgently needed." (PMID 34917120, 2021). "Our findings revealed the important roles of HSF2 across different cancer types." (PMID 35087869, 2021). "Additionally, the correlation of HSF2 expression with MSI was also explored in pan-cancer, among which READ, UCEC, and UCS exhibited a positive correlation while DLBC and PRAD exhibited a negative correlation with HSF2 expression." (PMID 35087869, 2021). "In addition, we investigated the alteration frequency of HSF2 in different cancer types according to the cBioPortal database." (PMID 35087869, 2021). "A deeper understanding of these differences may facilitate the development a global view to generate cancer development mechanisms with HSF2 expression." (PMID 35087869, 2021). "Moreover, we also investigated the expression of HSF2 in different cancer cell lines according to the Cancer Cell Line Encyclopedia (CCLE) database." (PMID 35087869, 2021). "Therefore, the aims of this study were to explore the expression profile, prognostic value, methylation level of HSF2, and potential relationship between HSF2 expression and immunological functions in 33 different types of cancer." (PMID 35087869, 2021). "As proteasome inhibition is an important strategy for the treatments of cancers, targeting HSF2 may be a valuable tool to reduce chemoresistance to proteasome inhibition." (PMID 35087869, 2021). "Based on our observations, targeting HSF2 may be a promising immunotherapeutic strategy for the treatment of specific cancers." (PMID 35087869, 2021). "When combining the data from TCGA and GTEx, HSF2 was dysregulated in up to 25 types of cancer." (PMID 35087869, 2021). "Here, we conducted the first comprehensive systematic analysis of HSF2 across 33 cancer types." (PMID 35087869, 2021). "First, we identified genes with positive or negative coexpression with HSF2 using the TCGA database, and the top 50 genes that were positively and negatively associated with HSF2 in different cancers are shown." (PMID 35087869, 2021). "A few studies have shown altered expression of HSF2 in cancer." (PMID 34917120, 2021). "HSF2 expression was dysregulated in the human pan-cancer dataset." (PMID 35087869, 2021). "The results of the current study reveal the varied expression of HSF2 in different types and stages of cancers, which suggests that the effects of HSF2 on oncogenesis may vary across different cancer types." (PMID 35087869, 2021).
cancer (continued). "Given the recent reports on other members of the HSF family influencing the growth and other properties of cancer cells, it will be important to conclusively map the genomic loci that are regulated by HSF2 and HSF4, either alone or in conjunction with HSF1 and other transcriptional regulators." (PMID 32408596, 2020). "Since in Hsf2−/− MEFs one of these two subunits is downregulated, this suggests that inhibition of HSF2 could be beneficial for the sensitization of cancer cells to proteasome inhibitors." (PMID 24212658, 2011). "However, our study showed that HSF2 is a cancer-promoting gene in HCC." (PMID 35606363, 2022). "Additionally, HSF2 expression was correlated with immune cell infiltration, immune checkpoint genes, and the tumor immune microenvironment in various cancers, indicating that HSF2 could be a potential therapeutic target for immunotherapy." (PMID 35087869, 2021). "HSF2 expression was significantly linked with the abundance of infiltrating CD4+ T cells in 12 types of cancer, CD8+ T cells in 16 types of cancer, B cells in 16 types of cancer, macrophages in 17 types of cancer, neutrophils in 18 types of cancer, and DCs in 18 types of cancer." (PMID 35087869, 2021). "Among the members of the HSF family, HSF1, HSF2, and HSF4 are widely expressed in various cancers and tissues." (PMID 39248163, 2024). "They found that HSF2 physically and functionally interacts with HSF1 across diverse types of cancer." (PMID 36430241, 2022). "Recently, Mendillo and his colleagues reported that HSF2 physically and functionally interacts with HSF1 across diverse types of cancer." (PMID 36430241, 2022). "If highly impactful data are obtained from the experiments using HSF2+/+ and HSF2−/− mice, it must be a significant progress in both HSF2 and cancer research fields." (PMID 36430241, 2022). "Compared to HSF2, it is now widely known that HSF1 and its target HSPs are positively related to cancer (tumor) development and progression." (PMID 36430241, 2022). "It is widely known that HSF2 interacts with HSF1, surprisingly, they performed The Cancer Genome Atlas (TCGA) gene expression analysis in 21 cancers and examined which HSF has highest expression." (PMID 36430241, 2022). "Here, to further estimate the relationships between HSF2 and the TME, we first examined the correlation of HSF2 expression and the abundance of different infiltrating immune cells across different cancer types." (PMID 35087869, 2021). "Our study implies that these compounds should be used cautiously if developed for cancer therapies, since GB and its derivative GBA are strong inducers of the HSR, in multiple cell types, by involving the dissociation of a HSP90-HSF1/HSF2 complex." (PMID 34331200, 2021). "The relationships between HSF2 expression level and TMB across different cancer types were also investigated." (PMID 35087869, 2021). "The expression level of HSF2 was markedly and positively correlated with TMB in many cancers, including ACC, BRCA, GBM, LAML, LUAD, and SKCM, but negatively correlated with TMB in ESCA, THCA, and PAAD." (PMID 35087869, 2021). "In GE2-HCC, top potential transcriptional activators included transcription factors with reported tumour-promoting activity in HCC and/or other cancer types, e.g., NKX6-1, POU2F1/2, cJUN, E2F1, HSF2, SRF, TFCP2 and NFY." (PMID 33541355, 2021). "In this review, we focus on the expression patterns and functions of HSF1, HSF2, and HSF4 in specific cancer types and on the key mechanisms regulating HSF-driven tumor progression." (PMID 32408596, 2020). "This review focuses on the expression patterns and functions of HSF1, HSF2, and HSF4 in specific cancer types, highlighting the mechanisms by which the regulatory functions of these transcription factors are modulated." (PMID 32408596, 2020). "We predict the differential expression of several transcription regulator genes (including HSF2, ARNT, MEF2A, ATF2 and YY1) that are strongly related to the cancer grade." (PMID 20025723, 2009).
cancer (continued). "In addition to the extensive involvement of HSF1 in cancer, both HSF2 and HSF4 have been shown to affect cancer cell proliferation and invasion, and altered expression of HSF5 is associated with several cancer types." (PMID 40457168, 2025). "Although both HSF-1 and HIF-1 are essential transcription factors for stress responses, a limited number of studies have reported that HSF family proteins, HSF2 and HSF4, promote transcription of HIF-1α and result in VEGFA expression in several cancer cell lines." (PMID 38081808, 2023). "In 2016, although HSF1 has been well recognized as a driver of carcinogenesis, the involvement of HSF2 in various cancers had not yet been explored." (PMID 36430241, 2022). "Nevertheless, HSF2 has not been largely studied in the cancer field, and its role in oncogenesis or pan-cancer is still unclear." (PMID 35087869, 2021). "Second, although the signaling pathways and prognostic value of HSF2 in different cancer types were explored, there were no in vitro or in vivo experiments to verify these findings." (PMID 35087869, 2021). "Therefore, we examined the relationship between HSF2 expression and OS, DSS, DFI, and PFI across different cancer types." (PMID 35087869, 2021). "We also used the xCell algorithm to further estimate the relationship between HSF2 expression and the level of infiltrating immune cells and found that HSF2 expression was significantly correlated with infiltrating CD4+ T helper (Th) cells and macrophages in most cancer types." (PMID 35087869, 2021). "In addition to HSF1, HSF2 is also overexpressed in Huh-7 and SMMC-7721 HCC cells, where it mediates extensive metabolic reprogramming that allows cancer cells to modulate their energy production requirements." (PMID 32408596, 2020). "To date, however, no specific HSF2 cancer signature has been identified, thereby emphasizing that further studies on HSF2 in cancer are warranted." (PMID 32408596, 2020). "Furthermore, in nude mice injected with MCF-7 cells, the removal of ALG3 from the cancer cells reduced both tumor development and HSF2 levels, which indicates a positive feedback between ALG3 and HSF2." (PMID 32408596, 2020). "Although increasing evidence indicates that HSF2 may play a vital role in the tumorigenesis of some specific types of cancers, a systematic pan-cancer analysis of HSF2 has not yet been conducted." (PMID 35087869, 2021). "The results implied that HSF2 expression was markedly correlated with the infiltrating level of B cells in 16 types of cancer, CD4+ T cells in 12 types of cancer, CD8+ T cells in 16 types of cancer, macrophages in 17 types of cancer, neutrophils in 18 types of cancer, and DCs in 18 types of cancer." (PMID 35087869, 2021). "Moreover, we explored the relationship between HSF2 expression and DSS in cancer patients." (PMID 35087869, 2021). "Considering that HSF1, HSF2, and HSF4 display multiple properties in cancer, which are either unique or common for each factor, or whether they act synergistically or antagonistically with each other, the need for new and improved agents targeting HSFs is significant." (PMID 32408596, 2020). "Therefore, APC/C, by its effect on HSF2, could be involved in a cell cycle-dependent manner in the modulation of HSF1 activity, which could have profound effects on cancer progression." (PMID 24212658, 2011). "However, compared with HSF1, HSF2 has not been extensively investigated in cancer, and its function and molecular mechanisms in oncogenesis are largely unknown." (PMID 34917120, 2021). "Indeed, HSF2 has a versatile — active or negative — impact on transcription, by acting as an activator of repressor, depending on the target gene and cellular state and environment considered cells lines, cancer cell lines, stress conditions, differentiation stages etc." (PMID 40318841, 2025). "Cancer experiments using HSF2+/+ and HSF2−/− mice have not been performed or reported yet." (PMID 36430241, 2022).
tumor (19 papers, 2010 to 2026). "The relationship between HSF2 expression and DNA methylation, immune infiltration of different immune cells, immune checkpoints, tumor mutation burden (TMB), and microsatellite instability (MSI) were analyzed using data directly from the TCGA database." (PMID 35087869, 2021). "Moreover, pathways associated with stress response, such as Hsf2 target genes, Hsf1 activation, and response to heat, also exhibited significant downregulation in tumor tissues." (PMID 41186645, 2026). "In addition, as Wnt/β-catenin/TCF signaling has been known to cause tumor formation with aberrant activation of the components in this signaling, and they also showed that HSF2 is targeted by Wnt/β-catenin/TCF signaling and contributes to tumor formation." (PMID 36430241, 2022). "In the present study, we found that HSF2 expression was negatively associated with the infiltration level of Th1 cells but positively correlated with the level of infiltrating Th2 cells in most tumor types." (PMID 35087869, 2021). "However, studies examining the expression and prognostic value of HSF2 and its association with tumor-infiltrating immune cells in HCC are still rare." (PMID 34917120, 2021). "Adoptive cell transfer (ACT) of tgTCR 47BE7+CD8+ T cells also delayed B16F10 tumour growth upon overexpression of Hsf2 p.K72N in the B16F10 tumour line." (PMID 38459027, 2024). "For the purposes of this study, vaccination and ACT serve as proof-of-concept that various immunotherapeutic modalities involving Hsf2 p.K72N can yield tumour growth control in vivo." (PMID 38459027, 2024). "HSF2 expression was also higher in HCC tissues than in para-cancerous tissues, and the HSF2 expression level increased with tumor stage." (PMID 35606363, 2022). "Taken together, these findings imply that there is a close relationship among HSF2, the inflammatory response, and the tumor microenvironment (TME)." (PMID 35087869, 2021). "Because immune checkpoint genes play an important role in tumor immunotherapy, the correlations between HSF2 and immune checkpoint genes, immunoinhibitors, and immunostimulators were subsequently analyzed." (PMID 35087869, 2021). "We estimated the association between HSF2 and immune cell infiltration using CIBERSORT to further assess the relationship between HSF2 and the tumor microenvironment (TME)." (PMID 34917120, 2021). "Patients with HCC presenting more advanced tumor grades tended to express higher levels of HSF2 than those with less advanced tumors." (PMID 34917120, 2021). "Gene expression was first analyzed in the TIMER database to validate the differential expression of HSF2 between various tumor tissues and adjacent normal tissues." (PMID 34917120, 2021). "The present study identified the expression of HSF2 mRNA in tumor tissues and compared it to normal liver tissues." (PMID 34917120, 2021). "Regarding tumor grade, HSF2 expression was significantly elevated in patients with grades 1, 2, 3 and 4 HCC, and the highest levels of HSF2 were observed in patients with grade 4 HCC." (PMID 34917120, 2021). "We further explored the relationships between HSF2 expression and various tumor-infiltrating immune cells in HCC using the TIMER and GEPIA databases by analyzing the different immune cell gene markers." (PMID 34917120, 2021). "Efforts are needed to develop novel drugs or RNAi techniques targeting HSF2 in tumor-infiltrative immune cells." (PMID 35087869, 2021). "ALG3 silencing significantly suppresses tumor growth and downregulates HSF2 expression, suggesting the presence of a feedback loop between these two genes." (PMID 35087869, 2021). "The expression of HSF2, ZO-1, occludin and claudin-5 in tumor microvessel segments was detected by Real-time PCR assay." (PMID 26078353, 2015).